EGFR (epidermal growth factor receptor)
Diseases named in the same sentence as EGFR in open-access papers (continued):
Sharing a sentence is not in itself a finding about the gene and the disease.
tumor (continued). "The activity of another oncogenic tyrosine kinase, Abl, downstream of EGFR and Src kinase facilitates invadopodia formation and promotes tumor cell invasion and metastasis." (PMID 25734659, 2015). "Patients with tumor NeuGcGM3+/EGFR+ had a significantly poorer OS than those with NeuGcGM3+/EGFR− phenotype (40.0% versus 68.2%; p < 0.000; Fisher's exact test)." (PMID 26634172, 2015). "ZD6474, a small molecule VEGFR and EGFR tyrosine kinase inhibitor, has been considered as a promising tumor-targeted drug in various malignancies." (PMID 26050198, 2015). "We performed 89Zr-cetuximab PET imaging in patients with wt K-RAS mCRC with an indication for anti-EGFR mAb monotherapy to investigate biodistribution and tumor uptake as well as to establish the optimal scanning time point to visualize tumor targeting." (PMID 26309164, 2015). "EGFR is overexpressed in numerous tumor types, including lung, head and neck, colon, pancreas, breast, ovary, bladder, and kidney cancer (reviewed in ref.25)." (PMID 25919378, 2015). "In cell line experiments, pemetrexed increased EGFR phosphorylation and reduced Akt phosphorylation, which ultimately enhanced the sensitivity of the tumor to EGFR TKIs." (PMID 26481697, 2015). "Several previous preclinical studies on other tumor entities have shown additive and super-additive but also antagonistic interactions for EGFR inhibitors and chemotherapy." (PMID 26526352, 2015). "Significant inhibition of tumor cell growth by dacomitinib was found in cells with high-EGFR expression (TE2 and TE3) in comparison to that against low-EGFR expressing HCE4." (PMID 26462025, 2015). "A representative tumor with concurrent EGFR L858R and MLH1 V384D mutations displayed primary resistance to EGFR-TKI treatment." (PMID 25823662, 2015). "This study investigated the sensitivity of erlotinib-resistant tumor cells to five cytotoxic agents using an in vitro EGFR-TKI-resistant model." (PMID 25875914, 2015). "As a result, EGCG drastically reduced epidermal growth factor-induced EGFR phosphorylation, which plays the crucial role in tumor cell growth and survival." (PMID 26135316, 2015). "These adhesion molecules also formed tight protein complexes and synergized with EGF/EGFR to accelerate tumor cell motility and invasion." (PMID 26377974, 2015). "EGFR mutation, KRAS mutation and ALK-IHC were investigated in the 14 patients whose tumor specimens were available." (PMID 26682906, 2015). "pUS-mediated MB treatment increased tumor vessel permeability, thus increasing delivery of targeting MBs and significantly enhancing anti-EGFR therapy in the tumor." (PMID 25960704, 2015). "Increasing tumor concentrations of lapatinib from 1–10 μM appeared to be associated with increased HER3 phosphorylation, and persistent phosphorylation of EGFR." (PMID 26571496, 2015). "Medical records review studies carried out in 2010 reported that over 94% of patients were being tested for tumor KRAS status prior to being treated with EGFR-targeted therapies." (PMID 26491871, 2015). "We conclude that the decreased expression of the tumor-suppressive miR-23b/27b cluster enhanced cancer cell proliferation, migration and invasion in BC through direct regulation of EGFR and c-Met signaling pathways." (PMID 25405368, 2015). "For example, CD4 T cells can promote progression through interaction with tumor-specific macrophages, which subsequently stimulate the EGFR pathway leading to tumor metastasis." (PMID 25991675, 2015). "The key role of EGFR in tumor growth is evident from the antiproliferative effects of monoclonal antibodies specific for this receptor." (PMID 26258011, 2015).
tumor (continued). "sEGFR, comprising only the extracellular domain of EGFR, is found in blood and can potentially reflect changes in tumor growth." (PMID 25992884, 2015). "The efficacy of CNX-2006 against cells expressing WT or mutant EGFR was evaluated in surrogate kinase assays and tumor cell lines." (PMID 26015408, 2015). "Because of its role on tumor progression, the EGFR has been intensely studied as a therapeutic target." (PMID 25672851, 2015). "Blocking this pathway by expressing a dominant-negative form of EGFR in progenitors of Sox21a flies suppressed the formation of tumour." (PMID 26690827, 2015). "The tumor-derived DNA was mixed with DNA from EGFR wild-type patients in ratios ranging from high to low tumor content (100 %–0 % tumor, serially diluted one in two times)." (PMID 26022577, 2015). "The results have shown significant reduced levels of phospho-CDK1T14/Y15, EGFR, and Ki-67 in tumor tissues after ganetespib treatment." (PMID 25590805, 2015). "Recent investigation has elucidated tumor cell-level mechanisms that account for suboptimal responses to HER2-targeted therapies, including overexpression of EGFR, cMYC, or ERBB3, and mutational loss of PTEN or activation of PI3K." (PMID 25997452, 2015). "It has been shown that patients with tumor mutations in KRAS exon 2 as well as KRAS exons 3 or 4 or NRAS exon 2, 3, or 4 are likely to show resistance to anti-EGFR agents." (PMID 26452027, 2015). "One of the important mechanisms by which inhibition of the epidermal growth factor receptor (EGFR) enhances tumor oxygenation is the regulation of VEGF." (PMID 26569225, 2015). "EGFR expression significantly correlated with tumor differentiation (P = 0.031), whereas CXCR4 expression significantly correlated with lymph node metastasis (P = 0.001)." (PMID 25679210, 2015). "Although mice with lung tumors driven by mEGFRL+T are resistant to reversible EGFR TKIs used as single agents such as erlotinib or afatinib, combinations of EGFR-directed therapies can decrease expression of EGFR and tumor size." (PMID 26027747, 2015). "This study shows anti-tumor activity with anti-EGFR retreatment in KRAS exon 2-wt CRC patients who had progressed on prior cetuximab- or panitumumab-based treatment." (PMID 26474549, 2015). "Taken together, these observations suggest that sEGFR protein is capable of inhibiting tumor cell proliferation and cell migration in NSCLC cell lines devoid of EGFR mutations in their TK domain." (PMID 26295387, 2015). "Overexpression of EGFR has been reported in human HCC, and is associated with the late stages of disease, increased cell proliferation and the degree of tumour differentiation." (PMID 25872741, 2015). "Although tumor samples are required for studying the mechanism of resistance to EGFR-TKIs, it is difficult to obtain such samples from patients with NSCLC who have acquired such resistance." (PMID 26334838, 2015). "Mice treated with a combination of BRAFV600E and EGFR inhibitors showed dramatic reduction in tumor growth and extended survival compared to vehicle or single drug treated counterparts." (PMID 26023796, 2015). "Activated EGFR recruits a number of downstream signaling molecules, leading to the activation of several pathways involved in tumor growth, progression, and survival." (PMID 26295387, 2015). "Athale and Deisboeck33 developed an ABM to examine the effects of a molecular switch (controlled via epidermal growth factor receptor (EGFR) signaling) on tumor spatial dynamics in the brain." (PMID 26783498, 2015). "Amplification of the epidermal growth factor receptor (EGFR) gene is a frequent occurrence in primary GBMs as well as mutations of phosphatase and tensin homolog (PTEN) tumor suppressor gene." (PMID 26287251, 2015).
tumor (continued). "In in vivo xenograft studies, monensin effectively inhibited xenograft tumor growth, perhaps by inhibiting cell proliferation through targeting EGFR signaling." (PMID 26639992, 2015). "The RAS/RAF/ERK pathway, which also plays an important role in tumor development, is downstream of EGFR." (PMID 25963410, 2015). "New biological agents mainly target two different pathways: tumor growth mediated by proangiogenic factors, and Epidermal Growth Factor Receptor (EGFR)-triggered cell proliferation." (PMID 26318427, 2015). "Treatment of A431 squamous cell carcinoma and breast carcinomas transfected with DCN cDNA resulted in tumor cell apoptosis, reduced EGFR signaling, and retarded tumor growth." (PMID 26697491, 2015). "EGFR overexpression has been found in over 80% NPC cases, and was associated with tumor metastasis, recurrence, and poor survival in patients with NPC." (PMID 29147412, 2015). "The combined treatment of WBRT with EGFR inhibitors in brain metastases from NSCLC resulted in a favorable tumor response and prolonged median survival with little toxicity." (PMID 26048754, 2015). "Several studies in human Rhabdoid tumor cells have demonstrated Lapatinib and Gefitinib as highly effective in inhibition of proliferation, consistent with high levels of EGFR / ErbB expression and signaling." (PMID 26370283, 2015). "To better define the role of tumor cell dependence on Src and EGFR, we tested Src inhibitors in combination with different classes of EGFR inhibitors at their equipotent doses." (PMID 26325669, 2015). "The EGFR protein expression level was detected in the assessable tumor tissues of 47 patients (57.3 % of the full analysis set population)." (PMID 25185971, 2015). "In summary, these results show that blocking both the FGFR1 and EGFR signaling pathways significantly delays tumor recurrence." (PMID 26581390, 2015). "EGFR restrains the maturation of specific tumor suppressor miRNAs, such as miR-31, -192, and miR-193a-5p, by phosphorylation of Argonaute 2 (AGO2) at Tyr393." (PMID 26287249, 2015). "For example, the GBM6 xenograft is derived from a patient with overexpression of the EGFRVIII mutant, and our finding of high EGFR expression in bulk tumor cells, and in tumors derived from them is consistent with EGFR overexpression." (PMID 25955030, 2015). "The ligand-dependent signalling of IGF-1R and EGFR is potentiated by P-cadherin in cell models or early tumour development." (PMID 26438065, 2015). "Knockdown of AR expression in HCC cells or blockage of EGFR signaling in Tregs enhanced CD8+ T cell-mediated anti-tumor response." (PMID 26451607, 2015). "At the same time, it was demonstrated that the KRAS gene, both in its wild and mutated state, was capable of predicting both the response and its utility in the tumour against the use of EGFR inhibitors." (PMID 25932044, 2015). "We present divergent cellular mechanisms associated with RTK-dependent and RTK-independent cell lines and provide in vitro and in vivo evidence demonstrating the anti-tumor efficacy of targeting EGFR/HER in the RTK-dependent subset." (PMID 25992771, 2015). "This method did allow for the detection of individual mutant KRAS and EGFR sequences in both plasma DNA and platelet RNA, indicating sequestration and potential education capacity of mutant, tumor-derived RNA biomarkers in TEPs." (PMID 26525104, 2015). "Advanced TNM stage, positive resection margins, poor tumor differentiation and EGFR/CXCR4 coexpression were independent unfavorable prognostic factors for both DFS and OS." (PMID 25679210, 2015). "For instance, anti-EGFRvIII antibodies, such as mAb 806 and CH12, which selectively bind to a cancer-specific epitope of EGFR or EGFRvIII, have been demonstrated to be capable of efficiently inhibiting the growth of EGFRvIII-positive tumor xenografts." (PMID 26474285, 2015).
tumor (continued). "In line with our previous report, we found that treatment of the EGFR-targeted drugs dramatically suppressed tumor formation driven by CTED4, CTED5, and CTED8 as compared to PBS control." (PMID 25826094, 2015). "Together, our findings highlight the role of CMTM7 in the regulation of EGFR signaling in tumor cells, revealing CMTM7 as a novel molecule related to Rab5 activation." (PMID 26528697, 2015). "Most oncology drug targets (e.g., Her2, EGFR) exhibit a quantitative expression difference between tumor and normal tissue." (PMID 26327203, 2015). "The present study shows that by eliciting mesenchymal and stem-cell-like traits and EGFR expression, the tumour intrinsic inflammatory mPGES-1/PGE2 pathway cooperates with the EGFR oncogene to promote an aggressive PCa phenotype." (PMID 26113609, 2015). "Although no expression of CD70 was found in biopsies showing ALK translocations and resistance or activating EGFR mutations, the biopsy with a T790M mutation revealed CD70 positivity in the tumor cells." (PMID 25951351, 2015). "EGFR is considered a suitable drug target for OSCC treatment because the majority of OSCC cells overexpressed EGFR, and high EGFR tumor levels are associated with poor clinical outcomes." (PMID 26462152, 2015). "Liquid biopsy, which helps to isolate circulating tumor DNA, is an innovative method to study both primary and acquired resistance to anti-EGFR monoclonal antibodies." (PMID 26318427, 2015). "Mice with a single intratumoral injection of EGFR-CAR cells had significantly decreased tumor burden, compared to those infused with HBSS or NK-92-EV cells." (PMID 26155832, 2015). "Similarly, considering the effect of EGFR-targeting tyrosine kinase inhibitors under reduced oxygen conditions, several studies indicated that treatment with gefitinib or erlotinib was associated with a dramatic reduction in the proportion of viable hypoxic tumor cells." (PMID 26032726, 2015). "In terms of a multiplexed molecular diagnostics, the HER2 and EGFR were identified clearly at the same time on the outer and cut tumor surfaces in the four mice with 75% and 100% accuracy, respectively." (PMID 25820115, 2015). "Previous studies showed that overexpression of EGFR occurred in BC and the expression level correlated with tumor grade, stage and survival." (PMID 25405368, 2015). "The importance of these co-existing mutations has been previously discussed in the CGP report, where enhanced sensitivity to ERBB2/EGFR targeting agents appears to be related to elevated EGFR expression in tumor cells with SMAD4_MUT." (PMID 26132924, 2015). "Our results thus support the notion that tumor cells harboring T790M are present in small numbers even before EGFR-TKI treatment, and that these T790M-positive cells undergo selection and enrichment during such treatment." (PMID 26015401, 2015). "EGFR is among the most promising molecules in the clinical management of this kind of tumor, considering its role in the carcinogenesis process and progression of NSCLC." (PMID 26295387, 2015). "TAE226 exerted a higher anti-tumor effect on the HEK-293T with the mutant EGFR than on the HEK-293T with the wild-type EGFR (the IC50 values were 0.41 ± 0.06 and 3.0 ± 0.11 μM, respectively)." (PMID 26090892, 2015). "RPPA performed to investigate the possible molecular mechanisms involved in tumor recurrence indicated that the recurrent tumors had elevated phosphorylated EGFR (p-EGFR) expression." (PMID 26581390, 2015). "Immunohistochemistry results of EGFR in ganetespib-treated tumor tissues confirmed that the protein levels of EGFR decreased markedly in vivo." (PMID 25590805, 2015).
tumor (continued). "Six major pathways perturbed by EGFR hyperactivity were identified and several of the regulated proteins are interesting drug target candidates and this includes tumour specific expression of kinases as well as proteins involved in aberrant metabolism." (PMID 25872475, 2015). "Human tumor cell lines that express EGFR at varying levels were xenografted subcutaneously in the flank of nude athymic mice." (PMID 25716578, 2015). "Here we demonstrate three-dimensional tracking of epidermal growth factor receptor complexes at a depth of ∼100 μm in tumour spheroids." (PMID 26219252, 2015). "Western blot analysis revealed that treatment of mice with honokiol inhibited the levels of EGFR as well as p-EGFR in tumor xenograft samples from both FaDu and SCC-1 cells compared to the tumor samples from the control mice." (PMID 26020804, 2015). "Xenografts of human GBM cell lines in rodents were demonstrated to develop blood vessels with human specific endothelial epitopes, harboring tumor specific molecular changes such as epidermal growth factor receptor (EGFR) amplification." (PMID 26203665, 2015). "In fact, ligand-independent, constitutively active forms of EGFR can increase motility and invasiveness of tumor cells, and EGFR inhibitors block cancer cell migration in vitro." (PMID 26635612, 2015). "This has also contributed to the approval of erlotinib for mutated EGFR tumors and crizotinib for ALK rearranged neoplasms." (PMID 25691052, 2015). "By contrast, only 7/25 (28%) of organ-confined tumours showed co-expression of mPGES-1 and EGFR (70.3% vs 28%, see also panel a and b from an organ confined PCa sample vs c and d from an advanced PCa sample)." (PMID 26113609, 2015). "In the targeted MB with pUS treatment group, EGFR antibody leaked outside vessels and spread through tumor tissues." (PMID 25960704, 2015). "EGFR activation has been shown to enhance processes responsible for tumor growth and progression, including the promotion of proliferation, invasion/metastasis, inhibition of apoptosis, and neoangiogenesis." (PMID 25699271, 2015). "This provided evidence that cetuximab delivery correlated with the expression of EGFR in almost all of the tumor tissues excised and provided significant insight into antibody compartmentalization not previously known or observable in humans." (PMID 26120042, 2015). "The observed small variation was understood probably due to the variation of the HER2/EGFR expression according to the size and physiological conditions of the tumor implants." (PMID 25820115, 2015). "From January 2010 to August 2013, 1797 FFPE tumor samples, derived from patients with mCRC, mMEL and NSCLC were selected to detect K-RAS, BRAF and EGFR somatic mutations, respectively." (PMID 25844806, 2015). "Western blot and WST-1 assays of EGFR siRNA-transfected HEC-1A, KLE, and Ishikawa cells were used to evaluate the efficacy of erlotinib in tumor cell lines expressing different EGFR levels." (PMID 26673416, 2015). "Our results highlight the clinical potential of molecular-based tumor targeting nanoparticles as gene therapy vehicles as well as the therapeutic benefit of TUSC2-erlotinib combination in wild type EGFR NSCLC." (PMID 26053020, 2015). "One molecule that has been shown to be involved in resistance to EGFR inhibitors in different tumor types is MET, the receptor tyrosine-kinase for hepatocyte growth factor (HGF)." (PMID 26319934, 2015). "Although the tumor volume was higher for EGFR mutants in our quantitative analysis, the differences were not significant, as previous work had demonstrated." (PMID 26337765, 2015). "The primary tumor was epidermal growth factor receptor (EGFR) positive and cetuximab, a monoclonal antibody to EGFR, was added." (PMID 26294988, 2015). "In particular, EGFR expression was evident in 29 out of 45 (64%) primary tumours, and in 10 of the 21 (48%) metastatic lesions." (PMID 25663927, 2015).